MTOR (mechanistic target of rapamycin kinase)
Diseases named in the same sentence as MTOR in open-access papers (continued):
Sharing a sentence is not in itself a finding about the gene and the disease.
bladder tumor (19 papers, 2011 to 2024). "This particular MTOR mutation is also present in the primary bladder tumor, but at a very low frequency (1%)." (PMID 30176882, 2018). "As such, we have devoted to evaluating the expression of STn and proteins associated with the activation of the PI3K/Akt/mTOR pathway activation in bladder tumours at different stages." (PMID 26569621, 2015). "Another event influencing mTOR pathway activation in bladder tumours involves the loss of tumor suppressor PTEN (phosphatase and tensin homolog deleted on chromosome ten) function." (PMID 26569621, 2015). "Development or selection of a subpopulation of cells with this activating MTOR mutation may be the driving event for lung metastasis within the primary bladder tumor." (PMID 30176882, 2018). "Thus, we think that the activating MTOR mutation could be one of the important drivers that lead to distant metastasis, perhaps thru evolution of a subclone of the low-grade bladder tumor." (PMID 30176882, 2018). "Bladder tumors are highly heterogeneous, with frequent mutations in different signaling pathways, including cell cycle genes, receptors’ tyrosine kinase, PI3K/AKT/mTOR, and chromatin regulatory gene mutations." (PMID 38397123, 2024). "The activation of the MAPK and PI3K/mTOR signaling pathways were reported in about 70% of bladder tumors, including amplification of EGFR (9%)." (PMID 39219681, 2024). "In this study, SHR-5 drinking exerts strong activities on the inhibition of mTOR signaling in vivo in bladder tumor tissues." (PMID 37370698, 2023). "The natural polyphenol, resveratrol, has been shown to slow the growth of bladder tumors in vivo and induce cell cycle arrest in vitro by inhibiting Akt/mTOR signaling, similar to the action of OMWW." (PMID 35057550, 2022). "Recent studies suggest that mTOR and phosphorylated mTOR expression in bladder tumors is correlated with an aggressive pathology." (PMID 35326708, 2022). "In support of this premise, we previously reported that the bioactive SFN combined with AZ upended the PI3K/Akt/mTOR survival signal transduction pathway in bladder tumor cells." (PMID 34316328, 2021). "Though PKC-alpha and RICTOR are in the mTOR signaling pathway in the bladder tumor, it is uncertain that the PKC-alpha and RICTOR are the mTOR signaling pathway." (PMID 32802870, 2020). "In vivo studies have shown that the inhibition of EGFR, VEGF, and mTOR suppresses bladder tumour growth." (PMID 32872665, 2020). "Deregulation of the PI3K/AKT/mTOR pathway was observed in more than 40% of bladder tumors and suggested the use of mTOR as a target for the treatment of urothelial cancers." (PMID 29454321, 2018). "BBN-induced mice bladder tumours mimicking the histology and molecular nature of human cancers, were screened for STn and pS6, the downstream effector of mTOR pathway." (PMID 26569621, 2015). "Our study also reinforced that bladder tumours present extensive activation of the PI3K/Akt/mTOR pathway irrespectively of their histological nature, as described in previous publications." (PMID 26569621, 2015). "Foreseeing a more accurate patient stratification we have also addressed the expression of PI3K/Akt/mTOR pathway markers in bladder tumours." (PMID 26569621, 2015). "Mice bearing advanced stage chemically-induced bladder tumours mimicking the histological and molecular nature of human tumours were then administrated with mTOR-pathway inhibitor sirolimus (rapamycin)." (PMID 26569621, 2015). "There has been little research into the levels of mTOR activation in bladder tumour tissue, with inconsistencies in the existing results." (PMID 25202348, 2014). "The AKT/mTOR pathway was markedly induced in bladder tumor cells with miR-222 upregulation." (PMID 37098542, 2023). "Taken together, our results suggest that salidroside may contribute to the effects of SHR-5 drinking on the inhibition of mTOR signaling and bladder tumor growth and progression." (PMID 37370698, 2023).
bladder tumor (continued). "MiR-222 inhibited autophagy via activating the AKT/mTOR axis in bladder tumor cells." (PMID 37098542, 2023). "Additionally, silenced Notch/JAG2 gene of BC cells, regardless of Mel treatment, was superior to Mel treatment for inhibiting the PI3K/AKT/mTOR signaling pathway, which in turn, suppressed the bladder tumor growth." (PMID 32792862, 2020). "A few studies have demonstrated positive associations between mTOR pathway activation and the clinicopathological parameters of bladder tumours, while others have failed to do so or have reported inverse associations." (PMID 25202348, 2014). "We investigated the effect of two dual PI3K/mTOR (both mTORC1 and mTORC2) inhibitors, NVP-BEZ235 and NVP-BGT226, on SQ20B laryngeal and FaDu hypopharyngeal cancer cells characterised by EGFR overexpression, on T24 bladder tumor cell lines with H-Ras mutation and on endothelial cells." (PMID 22452803, 2012). "MiR-222 enhanced bladder tumor cell proliferation and repressed CDDP-mediated apoptosis via regulation of PPP2R2A/AKT/mTOR axis." (PMID 37098542, 2023). "Other than targeting the PI3K/AKT/mTOR pathway, a recent study suggested that the inhibition of S6K1 and 4EBP1, its downstream effector proteins, helps control bladder tumor growth and progression." (PMID 35326708, 2022). "Altered protein glycosylation, translated by the expression of the STn antigen and its precursor Tn, PI3K/Akt/mTOR pathway molecules (pAkt, pmTOR, pS6), and PTEN inactivation, are salient features of bladder tumours." (PMID 26569621, 2015). "Bladder tumours often have not just one but several alterations in the expression of several components of AKT/PI3K/mTOR pathway suggesting the importance of synergistic effect of different tumour suppressors." (PMID 21283818, 2011). "Therefore, a retrospective design, 96 bladder tumours of different stages (Ta, T1-T4) was screened for STn and phosphorylated forms of Akt (pAkt), mTOR (pmTOR), S6 (pS6) and PTEN, related with the activation of the PI3K/Akt/mTOR pathway." (PMID 26569621, 2015). "As expected, immunohistochemical staining showed significantly increased expression of Gab1, phosphorylation of mTOR at Ser2481 and phosphorylation of AKT at Ser473 in both human and rat bladder tumor tissues but not in normal bladder tissues." (PMID 25596749, 2015).
Burkitt lymphoma (19 papers, 2013 to 2025). A rare form of malignant mature B-cell non-Hodgkin lymphoma. "Another study showed that HSP90 inhibitors were synergistic with dual PI3K/mTOR inhibition in Burkitt lymphoma driven by MYC dysregulation." (PMID 38475728, 2024). "In Burkitt’s lymphoma, EBV-mediated activation of the mTOR pathway correlated with fewer mutations in developed cancers, which the authors suggested was due to the presence of activated mTOR that bypasses the need for oncogenic mutations." (PMID 38612754, 2024). "Inhibition of mTOR/p70S6K/glycolysis signaling pathway is the key point of therapy in reversing GC resistant in Burkitt lymphoma patients." (PMID 26189041, 2015). "Finally, a previous study indicated that EBV uses mTOR-dependent pathways to increase metabolic activity in Burkitt’s lymphoma cell lines." (PMID 38612754, 2024). "While this paper did not identify the signals from LMP2A that are required to reach this effect, subsequent studies using this same mouse model of Burkitt’s lymphoma demonstrated that the mTOR inhibitor, rapamycin, blocks the LMP2A-mediated enhancement in tumor development." (PMID 38612754, 2024). "The effect of fisetin was analyzed on human Burkitt's lymphoma Raji cells through multiple processes including induction of apoptotic cell death, suppression of mammalian target of rapamycin (mTOR), and aberrant regulation of phosphatidylinositol‐3‐kinases (PI3Ks)." (PMID 33473265, 2021). "It has also been demonstrated that PI3K/mTOR signaling contributed to ABT-737 resistance in Burkitt lymphoma cells, and their inhibition through dual or active site mTOR inhibitors induced synergistic caspase activation, rendering chemoresistant cells sensitive to apoptosis induction." (PMID 26392332, 2015). "Our group and others have reported that recurrent genetic abnormalities have been observed in children with BL including the critical importance of the PI3K/Akt/mTOR pathway in Burkitt lymphomagenesis." (PMID 29774105, 2018). "The activation of PI3K/AKT/mTOR stabilizes the expression of c-Myc by upregulating HSP70, while c-Myc positively regulates the activity of mTOR to promote the survival of Burkitt’s lymphoma cells." (PMID 33494431, 2021). "Similar deregulation of PTEN and MIR17HG is also in place in Burkitt lymphoma (BL) cells, in which the constitute activation of the MYC oncogene that is due to chromosomal translocation also directly activates PI3K/AKT/mTOR." (PMID 32033478, 2020). "Further, in Raji cells (human Burkitt’s lymphoma cells), fisetin treatment activated the apoptotic process through inhibiting both PI3K and mammalian target of rapamycin (mTOR) signaling pathways." (PMID 31064104, 2019). "We aimed to confirm the effect of dual PI3K/mTOR inhibitor NVP-BEZ235 on cell proliferation and apoptosis in Burkitt lymphoma (BL) cells." (PMID 26130968, 2015). "In GCB DLBCL, PTEN deletions and amplification of the microRNA-17-92 cluster (MIR17HG) sustain cell proliferation, while similar deregulations are also in place in Burkitt lymphoma (BL) cells, in which the constitute activation of the MYC oncogene directly activates the PI3K/Akt/mTOR pathway." (PMID 37762410, 2023). "So far, it can be seen that the highly expressed transcription factor TCF3 in Burkitt lymphoma can recruit HDAC3 in the miR-101 promoter region, inhibit miR-101 expression, and regulate the activity of the Akt/mTOR pathway, thereby improving the biological performance of Burkitt lymphoma cells." (PMID 34658308, 2021). "Another group treating Burkitt lymphoma cells with the HSP90 inhibitor, PU176, also reported reduced tumor cell proliferation; however, they suggested the PI3K/AKT/mTOR pathway (but not MYC) as the main mechanism of action." (PMID 30453475, 2018).
cardiac rhabdomyoma (19 papers, 2016 to 2025). A well circumscribed benign tumor arising from cardiac muscle. "As a specific fetal manifestation of TSC, with the pathogenesis of cardiac rhabdomyoma involving TSC1 mutations that induce aberrant activation of the mammalian target of rapamycin (mTOR) pathway, resulting in abnormal myocardial cell proliferation." (PMID 41142004, 2025). "Current treatment strategies, such as mTOR inhibitors, offer potential effectiveness in managing associated cardiac rhabdomyomas." (PMID 37881637, 2023). "Cardiac rhabdomyomas in patients with TSC are linked to aberrant mTOR signalling through the loss of regulation by the hamartin (TSC1) and tuberin (TSC2) complex." (PMID 29744825, 2019). "Our patient had multiple inoperable cardiac rhabdomyomas causing serious left ventricle outflow-tract obstruction that showed a dramatic reduction in the size after everolimus therapy, a mammalian target of rapamycin (mTOR) inhibitor." (PMID 27429821, 2016). "After excluding non-eligible publications, a total of 20 documented cases were identified from 15 reports, all presenting lifesaving effects of mTOR inhibitors in fetuses and neonates with cardiac rhabdomyomas." (PMID 40933704, 2025). "All previously reported cases highlight the lifesaving effects of mTOR inhibitors in fetuses and neonates with cardiac rhabdomyomas." (PMID 40933704, 2025). "Recent study has reported successful treatment of fetal cardiac rhabdomyoma with mTOR inhibitors (everolimus or sirolimus) administered to the mother." (PMID 41142004, 2025). "Mechanistic/mammalian target of rapamycin (mTOR) inhibitors have been used successfully to reduce the size of cardiac rhabdomyomas." (PMID 40933704, 2025). "All previous reported cases present lifesaving effects of mTOR inhibitors in fetuses and neonates with cardiac rhabdomyomas; however, adverse effects cannot be disregarded." (PMID 40933704, 2025). "Therapeutic approaches with mechanistic/mammalian target of rapamycin (mTOR) inhibitors (such as everolimus and sirolimus) have been used successfully postnatally to reduce the size of cardiac rhabdomyoma." (PMID 40933704, 2025). "Only a few cases have reported prenatal treatment of cardiac rhabdomyoma with mTOR inhibitors, all of which showed a significant reduction in tumor size." (PMID 40722560, 2025). "Hitherto, there are few off-label studies that reveal effective usage of mTOR inhibition for cardiac rhabdomyoma." (PMID 30016967, 2018). "Firstly, although prenatal mTOR inhibition has been effective in reducing the size of cardiac rhabdomyomas, it remains unclear if this effect translates into improved long-term outcomes for the child, particularly in terms of neurological development." (PMID 39518472, 2024). "Reasons for initiation of mTOR inhibitor treatment were symptomatic cardiac rhabdomyomas and arrhythmia in 6 (35.3%), SEGA in 5 (29.4%), the combination of cardiac rhabdomyoma and SEGA in 1 (5.9%), refractory epilepsy in 4 cases (23.5%) and congenital focal lymphedema in 1 case (5.9%)." (PMID 31053163, 2019). "Everolimus, a mammalian target of rapamycin (mTOR) inhibitor, has been documented on various case studies to be effective and safe in treating patients with cardiac rhabdomyoma, particularly in tumors which are not resectable." (PMID 34629101, 2021).
colorectal tumor (19 papers, 2014 to 2025). "Another compound called atractylenolide I has been reported to exert anti-tumor activity against colorectal tumor progression via inhibition of CRC cell proliferation that is mediated by the AKT/mTOR signaling pathway." (PMID 36428613, 2022). "Another study indicated that the ATF4 pathway was activated, and the DDIT4 was upregulated to restrict mTOR and promote autophagy after inhibiting glutamine decomposition in colorectal tumor cells." (PMID 35013120, 2022). "In addition, total flavonoids from T. hemsleyanum, which mainly contain K3OR, rutinum, isoquercitrin, L-epicatechin, quercetin, astragalin, kaempferol 3-sambubioside, and catechin could inhibit the PI3K/AKT/mTOR pathway and thus delay colorectal tumor growth." (PMID 38611918, 2024). "The phosphatidylinositol 3-kinase/AKT/mammalian target of the rapamycin (PI3K/Akt/mTOR) signaling pathway plays a crucial role in the cell growth, proliferation and apoptosis and its dysregulations are common in a significant fraction of human malignancies, including colorectal tumors." (PMID 28972559, 2017). "The high glucose treatment of colorectal tumor shows an increase in proliferation and metastasis via the PI3K/AKT/mTOR pathway." (PMID 39337558, 2024). "Work from our group has shown that BCL-3 promotes colorectal tumour cell survival and growth in vivo, through activation of the AKT pathway via phosphoinositide 3-kinase and mammalian target of rapamycin (mTOR) signalling." (PMID 31930327, 2020). "We also demonstrated that O‐GlcNAcylation can mechanically increase the activation of the AKT/mTOR signalling pathway by regulating the expression of DDX5, thereby increasing the proliferation and metastasis of colorectal tumour cell lines." (PMID 30484950, 2019). "By using a phosphokinase arrays with human colorectal tumors we identified activated kinases, including the Epidermal Growth Factor Receptor (EGFR), components of the PI3K/mTOR pathway (AKT and S6), and STAT, among others." (PMID 26418718, 2015). "In contrast, the colorectal tumor milieu—characterized by high immune cell infiltration and distinct microbial and metabolic profiles—may shift FABP5’s function toward tumor-suppressive pathways, such as mTOR-dependent autophagy." (PMID 40717587, 2025).
emphysema (19 papers, 2016 to 2025). "mTOR signaling has been associated with cigarette smoke (CS)-induced COPD/emphysema through its crucial role in regulating autophagy and inducing cell senescence in COPD." (PMID 36468026, 2022). "Interestingly, lung cell senescence and development of emphysema was found to be associated with elevated mTOR activity in these mice, as the effects could be ameliorated by rapamycin (an mTOR inhibitor)." (PMID 30774592, 2019). "For instance, other biomarkers of aging, such as telomere shortening and oxidative damage to DNA and the mTOR pathway, are associated with both aging and COPD or emphysema." (PMID 39728428, 2024). "Given the pivotal inductive role of the lung mesenchyme in lung tissue development influencing both the epithelium and vasculature as well as COPD/emphysema, these findings illustrate the importance of mTOR signaling in these processes." (PMID 37874650, 2023). "Activation of the mTOR pathway is implicated in the accumulation of senescent cells during COPD, contributing to the development of emphysema by limiting tissue repair." (PMID 37874650, 2023). "A recent study claimed that the tuber extract of Alisma orientale alleviated airway inflammation and emphysema phenotype in mice by activating mTOR and inhibiting autophagy." (PMID 35134750, 2022). "The cytosolic transport (RNF126, PLEKHJ1, VPS51, and AP1G1), target of rapamycin (mTOR) signaling (PIK3CA, STK11, RPS6KB2, and PRR5), regulation of translation, metabolic regulation, and apoptosis are involved in the percent emphysema-associated network." (PMID 34777474, 2021). "Activation of the mTOR pathway is another mechanism by which cellular senescence may develop in emphysema." (PMID 35912114, 2022). "Furthermore, activation of the mTOR pathway through TSC1 deletion in either endothelial or AT2 cells was sufficient to drive the development of emphysema in mice." (PMID 35912114, 2022). "The inducible knockout of mTOR in mouse airway epithelial cells and alveolar type II epithelial cells will exacerbate smoking-induced inflammation, autophagy, necrosis, and apoptosis, which will lead to airway inflammation and emphysema." (PMID 35233217, 2022). "Thus, our findings support a significant role for mTOR in the maintenance of MVPC function and microvascular niche homeostasis as well as a cell-based mechanism driving loss of tissue structure underlying lung aging and the development of emphysema." (PMID 37874650, 2023). "Using complementary translational models, our data support a significant role for mTOR in the maintenance of human and mouse MVPC progenitor function via crosstalk with multiple signaling cascades as well as a cell-based mechanism underlying lung tissue remodeling and the development of emphysema." (PMID 37874650, 2023). "In studies on emphysema, UGCG has been proven to affect the apoptosis of pulmonary microvascular endothelial cells by regulating the mTOR pathway." (PMID 37274734, 2023). "Some studies have shown that PTEN/PI3K/AKT can regulate the polarization of macrophages in emphysema mice and induce apoptosis of alveolar epithelial cells in COPD by regulating autophagy through PI3K/AKT/mTOR pathway." (PMID 36309899, 2022). "We found the identified networks to be enriched in many biological processes including DNA repair, apoptosis, mTOR signaling, and metabolic regulation, which have been reported to contribute to the pathogenesis of COPD and emphysema." (PMID 34777474, 2021). "In contrast, mTOR signaling, which controls ALP and protein synthesis, was reduced by pulmonary inflammation (‘L’ and ‘E + L’) as well as emphysema as a single insult (‘E’) compared to control." (PMID 28464882, 2017). "Studies on emphysema and other related diseases have found that inhibiting UGCG expression can promote apoptosis of human pulmonary microvascular endothelial cells by inhibiting the activation of the mTOR pathway." (PMID 37274734, 2023).